INS (insulin)
Diseases named in the same sentence as INS in open-access papers (continued):
Sharing a sentence is not in itself a finding about the gene and the disease.
diabetes (continued). "A similar proportion of people were treated with insulin (62% vs 58%) and oral anti-diabetes agents including SGLT2 inhibitors, with fewer patients in the BMI ≥ 35 kg/m2 group on sulphonylureas (31% vs 39%)." (PMID 33757476, 2021). "All the patients either had a previous history of diabetes mellitus or developed increased blood sugar levels following Covid infection, and were kept on insulin to control their blood sugar levels." (PMID 35087975, 2021). "The islet is the organ that secretes insulin, and it is mentioned earlier that insulin secretion decreases in diabetes." (PMID 34026064, 2021). "Daily insulin injection therapy remains to be the standard care for patients with T1D, late-stage of T2D, and in some rare forms of diabetes." (PMID 34589059, 2021). "To study the response of insulin-treated zebrafish larvae to anti-diabetes drugs, we evaluated the pancreatic islet with glimepiride (GLM), ile-pro-ile (IPI) and acarbose (ABS) treatment." (PMID 34358068, 2021). "Previous clinical studies regarding patients with diabetes who had sepsis, the 30-day mortality rate was higher among those receiving insulin treatment than among those receiving oral antidiabetic agents." (PMID 34603199, 2021). "After 10 years diabetes duration insulin sensitivity was uniformly greater with CI than with PI (PI vs CI, 0.3 ± 0.1 vs 2.9 ± 1.6 min-1.mU-1." (PMID 34335462, 2021). "The VAI and the BRI, which are new markers of obesity, are good markers of visceral adiposity and insulin sensitivity and show good correlation and predictive ability for diabetes, cardiovascular disease, and hypertension." (PMID 34993251, 2021). "These diseases appear to have impaired glucose metabolism (e.g., brain dysfunction) or an inability to manage elevated insulin and glucose (e.g., cancer, diabetes)." (PMID 34631141, 2021). "These two processes prevent the availability of insulin needed for glucose uptake in the cells; hence, inducing hyperglycemia in diabetes." (PMID 34209371, 2021). "The transient recovery period of beta-cell function, after initiation of insulin therapy in patients with newly diagnosed type 1 diabetes mellitus, is referred to as the ‘honeymoon’ or partial remission phase (PRP)." (PMID 33485357, 2021). "After 6 weeks of intervention, supplementation with different dosages of GABA-enriched germinated adzuki beans significantly improved insulin sensitivity compared with that of the diabetes model group (M), and group M had the worst sensitivity." (PMID 34970582, 2021). "In astrocytes, knockdown of the lncRNA-TCF7L2 resulted in decreased expression of the parent gene, TCF7L2, as well as alterations in the expression of a series of genes involved in insulin signaling and diabetes." (PMID 34535768, 2021). "The olfactory track seems to interact with hormones, such as insulin, ghrelin, and leptin which play significant roles in body weight and glucose metabolism in subjects with diabetes mellitus." (PMID 34884338, 2021). "This indicated that the decreased NLRP3 inflammasome activity in NAG-1 Tg mice alleviates diet-induced obesity and enhances insulin sensitivity in the HFD/STZ-induced diabetic mouse model." (PMID 34294853, 2021). "The SLC29A2 gene which encodes the protein ENT2 (Equilibrative Nucleoside Transporter 2) has been proved sensitive to dysregulation in diabetes and acts as a target of insulin signaling." (PMID 34021221, 2021). "To date, few studies examining the role of insulin clearance in diabetes have simultaneously considered insulin sensitivity or insulin secretion." (PMID 34206745, 2021). "Dietary control, regular blood sugar monitoring, oral antidiabetic drugs, and insulin injections are now the main diabetes treatments." (PMID 33727934, 2021). "From a pharmacological standpoint, new insulin formulations have undoubtedly allowed higher efficacy, safety, and flexibility in the management of diabetes." (PMID 33755854, 2021).
diabetes (continued). "Diabetes-related plasma biomarkers insulin, leptin, resistin, and glucagon were significantly reduced by quercetin supplementation." (PMID 34439499, 2021). "Hyperuric acid has an independent effect on insulin secretion in diabetic patients and plays a key role in the evolution of diabetes mellitus (DM)." (PMID 35118005, 2021). "Diabetes mellitus management is mostly managed by the administration of insulin and antidiabetic oral drug consumption." (PMID 34804472, 2021). "A 55-year-old female patient with diabetes said: “During my one year of illness, I didn’t inject insulin until I was alone." (PMID 33461565, 2021). "The features of this app include wireless blood glucose data upload, recording of insulin use and exercise, on-demand direct access to a certified diabetes educator, and algorithms for pattern detection and assistance with day-to-day diabetes management." (PMID 33470947, 2021). "In the non-obese diabetic (NOD) model for autoimmune diabetes, mice null for either PD-1 or PD-L1 developed accelerated diabetes and significantly greater numbers of insulin specific T cells." (PMID 34803927, 2021). "Dapagliflozin is also indicated in patients with heart failure with reduced ejection fraction (HFrEF) independently of diabetes status and, in Europe, as an adjunct to insulin in T1DM." (PMID 34068655, 2021). "Many diabetics manage their condition using insulin, which requires appropriate storage conditions to maintain its stability and effectiveness." (PMID 34136581, 2021). "Mesenchymal stem cell (MSC) therapy is an innovative approach in diabetes due to its capacity to modulate tissue microenvironment and regeneration of glucose-responsive insulin-producing cells." (PMID 34926699, 2021). "The relationship between obesity and diabetes is made by a progressive defect or decrease in insulin secretion as well as coupled with a progressive increase in insulin resistance." (PMID 34162414, 2021). "TZD has been known to improve glycaemic control in type 2 diabetes mellitus (T2DM) by increasing insulin sensitivity in the body." (PMID 35194439, 2021). "In the hyperglycaemic group, 18 (72%) patients had prior history of diabetes and 15 (60%) were treated with an insulin infusion until they reached a BG level <140 mg/dL." (PMID 33063540, 2021). "Chronic exposure of pancreatic β cells to high levels of stearic acid (C18:0) leads to impaired insulin secretion, which accelerates the progression of type 2 diabetes mellitus (T2DM)." (PMID 34022799, 2021). "Despite the availability of a wide range of glucose‐lowering therapies many patients with type 2 diabetes mellitus (T2DM) need insulin therapy because of progressive pancreatic β‐cell failure." (PMID 33098260, 2021). "The glucagon-like peptide 1 receptor (GLP1R) is a therapeutic target for diabetes due to its involvement in insulin release through stimulation of the adenyl cyclase, with several GLP1 agonists currently in clinical use." (PMID 34944640, 2021). "These insulin-loaded, quick-dissolving microneedles were applied to the rats with diabetes for in vivo analyses." (PMID 33466845, 2021). "Of interest, placental exosomes from normoglycemic women increased insulin migration and glucose uptake in skeletal muscle of women with diabetes." (PMID 34764939, 2021). "Annual cardiology follow-up was seen in 21.5% of patients with diabetes in 2019 (up 1.1% from 2018) and was more common in insulin-treated patients (23.6% versus 20.4% in 2019)." (PMID 34917037, 2021). "Among patients with type 2 diabetes using insulin, more frequent SMBG was associated with improved glycemic control, especially in patients with uncontrolled diabetes at baseline." (PMID 34695917, 2021). "The ability of beta cells to detect and respond to varying glucose concentrations by modulating the secretion of insulin has long been considered as the major factor maintaining glucose homeostasis and explaining glucose dysregulation in diabetes." (PMID 33241460, 2021).
diabetes (continued). "A total of 7534 patients from 14 trials was treatment-naïve, whereas 67,340 patients received background treatment for diabetes with OADs and/or insulin." (PMID 32314085, 2021). "After 100 years, despite all the major advances in insulin therapy and blood glucose monitoring, hypoglycemia still remains the dark side of insulin, the major barrier preventing the full realization of its promise in diabetes management." (PMID 34572493, 2021). "Insulin and C-peptide are important in the diagnostics and management of metabolic disorders such as diabetes mellitus and are also particularly relevant target analytes in professional sports and forensics." (PMID 34065812, 2021). "Carotenoids have protective effects against T2DM and have shown a role in the treatment of diabetes, via enhancing insulin sensitivity, and its complications such as nephropathy and infectious diseases." (PMID 33917044, 2021). "Type 1 diabetes mellitus (T1D) results from the destruction of insulin-producing β cells in the islet of the pancreas by lymphocytes." (PMID 34067829, 2021). "Youth (6–17 years) with T1D and receiving insulin therapy were enrolled at a week‐long diabetes camp." (PMID 34277978, 2021). "In this time insulin therapy emerged as an indispensable tool in the arsenal of therapies used for diabetes management across the globe." (PMID 34924015, 2021). "Another source of insulin includes donation programmes, such as Life for a Child or Novo Nordisk’s Changing Diabetes in Children." (PMID 33483763, 2021). "Type 2 diabetes mellitus (DM) is a metabolic disorder characterized by insulin resistance and insulin hyposecretion that result in hyperglycaemia." (PMID 35186868, 2021). "Insulin treatment had a higher prevalence of diabetes distress than oral hypoglycemic agents or diet modification." (PMID 35002853, 2021). "In the pathogenesis of type 2 DM, impaired insulin sensitivity and insulin secretion were found to be major factors involved in the progression of diabetes." (PMID 33730054, 2021). "Diabetes is a complex metabolic disorder affecting the glucose status of the human body, characterized by impaired action, secretion of insulin or both, resulting in hyperglycemia." (PMID 33804123, 2021). "It was more if I had just usual diabetes again, if I had to have the injections for insulin medications that he would be there to help monitor me and everything like that." (PMID 34706727, 2021). "Diabetes includes a group of chronic metabolic disorders identified by hyperglycemia resulting from disrupting insulin secretion or action." (PMID 34572503, 2021). "Our study investigated the frequency of blood glucose monitoring and the methods adopted to measure, record, and share SMBG results by patients with diabetes and on treatment with insulin." (PMID 34704954, 2021). "Diabetes is a common metabolic disorder identified by abnormally high blood glucose levels and the insufficiency of secretion or function of endogenous insulin." (PMID 34094022, 2021). "Less than half (47.3%) of participants with diabetes in Mexico were consuming a special diet for diabetes and only approximately half (52.8%) of participants with diabetes in India were taking insulin or blood sugar lowering medication." (PMID 34789208, 2021). "These roles appear during the process of socialization of adolescents with diabetes, where commensality and situations of self-monitoring or administering insulin, key aspect of diabetes treatment, are crucial." (PMID 33672506, 2021). "It is suffering to have diabetes, you must pay attention to your diet, physical activity, and insulin injection." (PMID 34867789, 2021). "It has been reported that autophagy is involved in insulin resistance following endoplasmic reticulum stress in diabetes and differentially regulates insulin production and insulin sensitivity." (PMID 34956177, 2021).
diabetes (continued). "For the evaluation of DPP4 inhibitors, animals such as KKAy and ICR treated with streptozotocin and HFD to induce mild diabetes were used as DPP4 inhibitors improves glucose tolerance and insulin sensitivity in these mild diabetes models." (PMID 34373487, 2021). "Ischemic brain damage is much more pronounced in rats with diabetes mellitus than in healthy animals, as a result of which systemic treatment of diabetic animals with insulin weakened the severity of ischemic lesions." (PMID 34769198, 2021). "I am now 45 years old, and also have diabetes mellitus arising during pregnancy, furthermore I am on diet control as well as insulin injections to control blood sugar." (PMID 33407245, 2021). "The significance of insulin release is evident from a diabetes experimental model showing a decreased amount of bone-implant contact, which was restored with insulin therapy." (PMID 34835740, 2021). "Self-monitoring of blood glucose is an important part of diabetes self-management in patients receiving insulin therapy; it is useful for patients for adjusting insulin dosage and guiding nutrition therapy and physical activity." (PMID 33544081, 2021). "Metformin is currently one of the most widely used glucose-lowering drugs in the world, which can reduce blood sugar, regulate blood lipids, improve insulin sensitivity, and prevent the progression of diabetes." (PMID 34691233, 2021). "Insulin resistance (IR) is a pathological condition defined by the inability of insulin to stimulate glucose disposal and is considered as a key player in the development of type 2 diabetes mellitus." (PMID 34690773, 2021). "These bacteria can produce butyric acid to promote insulin secretion after meals and improve diabetes." (PMID 34805250, 2021). "Unequal distributions were evident for gender (P = 0.003), diabetes presence (P = 0.036), antihyperglycemic (P = 0.003), insulin (P = 0.003), and antilipemic (P = 0.035) users between tSHG tertiles." (PMID 33936384, 2021). "By combining total pancreatectomy with islet transplantation, patients can maintain some beta cell mass with insulin secretory capacity, in order to mitigate the severity of post-operative diabetes." (PMID 33776933, 2021). "Another natural plant resource for diabetes therapy, saponins from Gynostemma pentaphyllum (GPs) ameliorated hyperglycemia, dyslipidemia, and significantly increased insulin levels in STZ-induced diabetic rats." (PMID 33803588, 2021). "Although heterogenous in its manifestations and mechanisms, diabetes occurs and progresses when pancreatic beta cells fail to produce sufficient amounts of insulin to regulate blood glucose levels and other metabolic processes." (PMID 34440644, 2021). "Pioglitazone in clinical use is thought to enhance peripheral insulin sensitivity as a diabetes therapeutic agent; however, these supportive data also demonstrate direct effects of PPARγ agonists in the functional preservation of β-cells." (PMID 34592314, 2021). "a failure to measure or consider the pre-study dietary intake of the participants, and/or differences between studies in relation to other baseline characteristics (such as duration of diabetes, baseline HbA1c, or insulin sensitivity)." (PMID 34336909, 2021). "For example, the Diabetes Surgery Summit (DSS) recommends that patients using insulin and patients with disease duration longer than 5 years be prioritized." (PMID 33479921, 2021). "Among these, the β-cells that express both insulin and the transcription factor Nkx6.1 seem to be the most efficient to restore normoglycemia in diabetes animal models." (PMID 34025576, 2021). "During the COVID-19 lockdown, poor adherence to care contributed to diabetes mellitus onset needing high insulin requirements." (PMID 34078438, 2021). "Diabetes mellitus, a long‐term metabolic disease, is characterized by elevated glucose levels in the blood due to insulin secretion, insulin action, or both." (PMID 34925813, 2021).
diabetes (continued). "In other words, bariatric surgery has the potential to treat diabetes by increasing the likelihood of insulin independency, improving incretin secretion, recovering islet function, and restoring peripheral insulin sensitivity to regulate glucose homeostasis." (PMID 34827579, 2021). "She had also recently experienced a worsening of her diabetes control despite being on a basal-bolus insulin regimen." (PMID 34321093, 2021). "Recent studies in diabetes management presented the most common types of systems, which are insulin self‐management apps, wearable blood glucose monitors, automated SMS risk alerts and virtual diagnostician coaching." (PMID 34035925, 2021). "Supporting people with diabetes in insulin dosing and diet planning via information technology has gained much attention and is an active research area." (PMID 34209125, 2021). "IR‐A and IR‐B isoforms are involved in pathophysiological processes triggered by insulin, including development, differentiation, metabolism as well as obesity, diabetes, and cancer." (PMID 34841688, 2021). "For instance, severe metabolic conditions, such as diabetes mellitus, emerge when the endocrine β cells stop producing insulin (diabetes type 1) or the peripheral tissue becomes insensitive for the secreted insulin (diabetes type 2)." (PMID 34209288, 2021). "Treatment and management of diabetes include a healthy diet, physical exercise, medications to lower blood sugar levels, and insulin therapy." (PMID 34257624, 2021). "After surgery, the patient developed diabetes, which was poorly controlled with intensive insulin therapy." (PMID 33807230, 2021). "In this respect, it is incredible to think that a century later, insulin remains a vital mainstay in the management of Type 1 diabetes mellitus (T1DM)." (PMID 34093449, 2021). "Mice homogenous for hIAPP spontaneously develop diabetes due to β cell death, impaired insulin secretion, and hyperglycemia." (PMID 34027899, 2021). "We utilized Aetna administrative claims data to identify insulin-using people with diabetes with service dates from 01 January 2015 to 30 June 2018." (PMID 34238287, 2021). "Insulin therapy is one of the key strategies in managing diabetes in pregnancy, when nutritional therapy (NT) and lifestyle changes alone are not enough for an adequate glycemic control." (PMID 33767671, 2021). "Despite these limitations, this MVL with its modified membrane offers a clinical opportunity for glucose-responsive insulin delivery and is expected to maintain blood glucose homeostasis precisely to reduce the complications in patients with diabetes." (PMID 35056918, 2021). "The Hajj journey presents specific challenges for pilgrims with diabetes, including in relation to insulin handling and storage." (PMID 34136581, 2021). "Islet plasticity is of interest for the design of future treatments of diabetes through the production of mature surrogate insulin-producing cells." (PMID 33888791, 2021). "Inhibiting AMPK blocked the effects of NAR in improving insulin sensitivity and attenuating diabetes mellitus." (PMID 34163366, 2021). "Her twin sister, mother, maternal aunt, maternal grandmother also had insulin-requiring diabetes (from 8–12 units to 20–25 units daily)." (PMID 34032641, 2021). "Insulin insensitivity and deficiency compromise the blood regulatory mechanisms in patients with diabetes, thereby leading to hyperglycemia—a characteristic feature of DM." (PMID 34885816, 2021). "The most common forms of monogenic diabetes share residual insulin secretion, leading to the detection of C-peptide, which distinguishes MODY from severe type 1 diabetes." (PMID 35002955, 2021). "Insulin sensitivity, which is one of mechanism of diabetes, is improved by moderate to high level of PA." (PMID 33572718, 2021). "Access to insulin therapy had been limited until the age of 9, resulting in poorly controlled diabetes." (PMID 34419042, 2021).